LINC01118 (long independently transcribed non-coding RNA 1118)
Synonyms: LINC01119; LOC124906004
Gene: Long non-coding RNA gene on chromosome 2 (46,698,940 to 46,913,231, forward strand). Ensembl gene ENSG00000222005.
Diseases named in the same sentence as LINC01118 in open-access papers:
LINC01118 is named in the same sentence as 9 diseases in open-access papers, as found by Europe PMC text mining. Sharing a sentence is not in itself a finding about the gene and the disease.
LINC01118 shares sentences with these, for which no sentence is quoted: breast (2 papers); colorectal cancer (2); osteoporosis (2); breast carcinoma (1); cancer (1); cervical cancer (1); lentivirus infection (1); lung carcinoma (1); ovarian carcinoma (1).